CAP1 (cyclase associated actin cytoskeleton regulatory protein 1)
Diseases named in the same sentence as CAP1 in open-access papers (continued):
Sharing a sentence is not in itself a finding about the gene and the disease.
leukemia (3 papers, 2017 to 2022). A malignant (clonal) hematologic disorder, involving hematopoietic stem cells and characterized by the presence of primitive or atypical myeloid or lymphoid cells in the bone marrow and the blood. "CAP1 was overexpressed in most cancers, including bladder, head and neck, leukemia, lung, lymphoma, melanoma, pancreatic, and sarcoma cancer." (PMID 34636991, 2022).
melanoma (3 papers, 2016 to 2022). A malignant, usually aggressive tumor composed of atypical, neoplastic melanocytes. "Finally, this work allowed proposing TYRP1, cofilin-1 and CAP1 as potential markers to detect melanomas with varying degrees of aggressiveness." (PMID 27206672, 2016).
metabolic syndrome (3 papers, 2024 to 2025). A cluster of metabolic risk factors for CARDIOVASCULAR DISEASES and TYPE 2 DIABETES MELLITUS. "Their findings demonstrated that CEL bound to CAP1 disrupted the interaction between resistin and CAP1, and effectively attenuated the ensuing inflammatory response, which ultimately ameliorated metabolic syndrome." (PMID 40873643, 2025). "Resistin, an important adipokine, upregulates fatty acid oxidation (FAO) in synovial cells via the CAP1/PKA/CREB signaling pathway, thereby promoting inflammation and a catabolic phenotype that further exacerbates the progression of metabolic syndrome-related knee OA (MetS-KOA)." (PMID 41245401, 2025).
metastatic cancer (3 papers, 2016 to 2022). A carcinoma which has spread from the original site of growth to another anatomic site. "Elevated expression of both human CAP isoforms (CAP1 and CAP2) is linked to poor prognosis in multiple different metastatic cancers." (PMID 31718088, 2019). "Opposing to the case in the metastatic cancer cells, CAP1 knockdown in the MCF-7 cells reduced the activity of ERK1/2 instead, whereas no significant changes in GSK3 activity was observed (not shown)." (PMID 27173014, 2016). "Knockdown of CAP1 in metastatic cancer cells stimulated migration and invasion, similar to the case in HeLa cells." (PMID 27173014, 2016). "Thus, activation of integrins/FAK through an inside-out signaling by CAP1 knockdown in metastatic cancer cells has most likely directly activated ERK, which may subsequently inactivate GSK343." (PMID 27173014, 2016). "CAP1 depletion substantially stimulated the migration capability in both the BT-549 and MDA-MB-231 metastatic cancer cells, which is very similar to the case in HeLa cells." (PMID 27173014, 2016).
prostate carcinoma (3 papers, 2017 to 2019). A carcinoma that arises from epithelial cells of the prostate gland. "The cBioPortal analysis found that the frequency of 40.2–20% with the rank order mainly in prostate cancer with CAP1 and CAP2 alteration ranged from 38.3–19.8%." (PMID 28423713, 2017). "The cBioPortal and Tumorscape analysis found that frequency of 40.2–20% with the rank order mainly in prostate cancer with CAP1, CAP2 alteration ranged from 38.3–19.8%." (PMID 28423713, 2017). "The percentages of alterations in these genes among prostate cancer varied from 13-30% for individual genes (CAP2, 19%; CAP1, 13%; CFL1, 30%; CFL2, 21%; DSTN, 19%); the CFL1 gene was amplified predominantly in the prostate cancer type." (PMID 28423713, 2017). "For example, percentages of alterations in CAP2, CAP1, CFL1, CFL2, DSTN, ACTB, and ACTG1 genes among prostate cancer varied from 2.6–30% in individual genes (CAP2, 19%; CAP1, 13%; CFL1, 30%; CFL2, 21%; DSTN, 19%; ACTG1, 2.6%; ACTB, 21%;); the CFL1 gene was amplified predominantly in prostate cancer." (PMID 28423713, 2017).
breast tumor (2 papers, 2018 to 2020). "Higher CAP1 expression was found among ER− breast tumors, while lower expression was found among ER+ tumors." (PMID 30524378, 2018). "Whereas CAP1 gene overexpression consistently appears correlated to reduced cancer survival, few studies have reported the prognostic relevance for the corresponding protein level in breast tumor tissue." (PMID 32560703, 2020).
candidiasis (2 papers, 2021 to 2026). Infection with the organism Candida. "The CAP1 C-terminal truncations conferred significant fitness advantages in the presence of fluconazole, both in vitro and in a murine model of candidiasis." (PMID 41628278, 2026). "A study by Na and Song demonstrated that inhibition ELISA with a monoclonal antibody (CAP1) is effective in the detection of thee circulating SAP antigen and that this assay may be useful for the diagnosis and treatment monitoring of invasive candidiasis." (PMID 34946982, 2021).
COVID-19 (2 papers, 2024 to 2025). A disease caused by infection with severe acute respiratory syndrome coronavirus 2. "In the cohort of patients with COVID-19, CAP1 and CAP2 subphenotypes assigned by the PCM differed by key clinical characteristics and revealed an interaction between corticosteroid treatment and mortality (P = 0.002)." (PMID 41209652, 2025).
endothelial dysfunction (2 papers, 2025). In vascular diseases, endothelial dysfunction is a systemic pathological state of the endothelium (the inner lining of blood vessels) and can be broadly defined as an imbalance between vasodilating and vasoconstricting substances produced by (or acting on) the endothelium. "Through its engagement with key receptors, notably TLR4 and CAP-1, resistin activates a cascade of proinflammatory signaling pathways, including NF-κB and MAPK, which drive endothelial dysfunction, promote leukocyte adhesion and migration, and initiate early atherosclerotic processes." (PMID 41347124, 2025).
esophageal squamous cell carcinoma (2 papers, 2015 to 2020). Esophageal squamous cell carcinoma (ESCC) is a type of esophageal carcinoma (EC) that can affect any part of the esophagus, but is usually located in the upper or middle third. "CAP1 overexpression has been shown to be significantly associated with lymph node status in esophageal squamous cell carcinoma." (PMID 25652936, 2015).
head and neck squamous cell carcinoma (2 papers, 2022). A squamous cell carcinoma that arises from any of the following anatomic sites: lip and oral cavity, nasal cavity, paranasal sinuses, pharynx, larynx, and salivary glands. "Actin-binding proteins, including cofilin (CFL1), profilin 1 (PFN1), and adenylate cyclase-associated protein 1 (CAP1), are thought to be involved in tumor cell motility and metastasis, specifically in head and neck squamous cell carcinoma (HNSCC)." (PMID 37226274, 2022).
Hypertension (2 papers, 2022 to 2023). The presence of chronic increased pressure in the systemic arterial system. "CAP1/Prss8 was linked to hypertension in rats when overexpressed, to a moderate increase of human blood pressure in a genetic variant of CAP1/Prss8, and proposed as a urinary candidate marker of ENaC activation in humans." (PMID 37830556, 2023). "It is interesting to note a significantly higher prevalence of the C allele of the CAP1/Prss8 (prostasin, rs12597511) gene in hypertensive pregnant women highly suggesting that this allele might present a risk for hypertension and cardiovascular diseases." (PMID 35743186, 2022).
influenza (2 papers, 2023 to 2024). An acute viral infection of the respiratory tract, occurring in isolated cases, in epidemics, or in pandemics; it is caused by serologically different strains of viruses (influenzaviruses) designated A, B, and C, has a 3-day incubation period, and usually lasts for 3 to 10 days. "The combined modification of N1mΨ-UTP and Cap-1 effectively balances inflammatory responses while enhancing adaptive immunity, particularly in influenza vaccine models." (PMID 39203999, 2024). "To determine factors that promote CAP1 response to acute lung injury, we analyzed single-cell RNA sequencing (scRNA-seq) data from non-immune (CD45-negative) cells of the whole mouse lung at homeostasis and 14 days post-H1N1 PR8 influenza injury." (PMID 37233732, 2023).
non-small cell lung carcinoma (2 papers, 2022). A group of at least three distinct histological types of lung cancer, including non-small cell squamous cell carcinoma, adenocarcinoma, and large cell carcinoma. "The expression of CAP1 in non-small-cell lung cancer increased during growth of the primary tumor." (PMID 35237592, 2022).
osteoarthritis (2 papers, 2017 to 2023). A noninflammatory degenerative joint disease occurring chiefly in older persons, characterized by degeneration of the articular cartilage, hypertrophy of bone at the margins and changes in the synovial membrane. "The expression of resistin and CAP1 in synovial tissue was stronger in RA than in osteoarthritis (OA)." (PMID 29191223, 2017).
viral infection (2 papers, 2022 to 2023). "In M. japonicus miR-71 targeted the calcification-associated peptide-1 (cap-1) to regulate viral infection and host autophagy in shrimps." (PMID 37624033, 2023). "Recently, the crucial role of cap1 in distinguishing between ‘self’ and ‘non-self’ in mammalian cells during viral infection was revealed." (PMID 36018811, 2022).
Alzheimer disease (1 paper, 2019). A progressive, neurodegenerative disease characterized by loss of function and death of nerve cells in several areas of the brain leading to loss of cognitive function such as memory and language. "Further to this, Ginsenoside Rd has been shown to decrease levels of apoptotic proteins such as PARP1 and Bax, via adenylate cyclase-associated protein 1 (CAP1) regulation in an in vitro model of Alzheimer’s disease." (PMID 31771121, 2019).
asthma (1 paper, 2018). "Furthermore, one of the limitations of the current study is that we cannot exclude that asthma status may have an influence on gene expression of CFLAR and CAP1." (PMID 30127367, 2018).
bacteremia (1 paper, 2025). "Patients assigned to CAP1 also had more frequent bacteremia." (PMID 41209652, 2025).
bladder cancer (1 paper, 2017). "CAP1 mutation mainly occurred in bladder cancer and existed in a hotspot in the CAP N domain." (PMID 28423713, 2017).
cervical cancer (1 paper, 2022). A primary or metastatic malignant neoplasm involving the cervix. "Some of the most promising cervicovaginal fluid-based biomarkers for cervical cancer found until now are ACTN4, VTN, ANXA1, ANXA2, CAP1, and MUC5B." (PMID 35645371, 2022).
depression (1 paper, 2024). "Decreased entropy of Markov trajectories from CAP1 (SCN) to CAP3 (SCN−-CN−) (r = −0.1929, P = 0.004), within CAP3 (SCN−-CN−) (r = −0.1596 P = 0.0176), CAP7 (DMN−-ATN−) to CAP3 (SCN−-CN−) (r = −0.1475, P = 0.0284) were associated with elevated depression severity." (PMID 38172115, 2024).
emphysema (1 paper, 2016). "Consistently, supplemental analysis revealed that heterozygous deletion of CAP-1/prostasin/Prss8, one of the major CAPs that positively regulates ENaC, did not improve COPD/CF-like phenotypes such as emphysema and lung dysfunction." (PMID 27982104, 2016).
glomerular diseases (1 paper, 2017). "Immunohistochemistry staining for validation targets, CAP1, SHC1 and PRCP, was performed on eight IgAN, three other glomerular diseases and one healthy control slides of kidney tissue." (PMID 28831120, 2017). "CAP1 showed negative/below limit of detection (−) staining in the normal kidney, negative (−) to strong (+++) staining in other glomerular diseases and weak (+) to strong (+++) staining in tubules and glomeruli with noticeable staining in inflammatory cells in the IgAN group." (PMID 28831120, 2017).
head-neck cancer (1 paper, 2017). "Co-expression analysis revealed that CAP1 was coexpressed with TUBA1B both in pancreatic and head-neck cancer, as well as with CFL1, CFL2, DSTN, and ROBO1, according to STRING analysis." (PMID 28423713, 2017). "The co-expression analysis revealed that CAP1 was coexpressed with TUBA1B in pancreatic and head-neck cancer, as well as with CFL1, CFL2, DSTN, ACTB, ACTG1, and ROBO1, according to the STRING analysis." (PMID 28423713, 2017). "CAP1 was co-expressed with Tubulin alpha-1B chain (TUBA1B) in both pancreatic and head-neck cancer." (PMID 28423713, 2017).
HIV-1 infection (1 paper, 2010). The type species of lentivirus and the etiologic agent of acquired immunodeficiency syndrome (AIDS). "CAP-1 acts in the late stage of viral replication and does not inhibit HIV-1 infection when added to pre-formed HIV-1 particles." (PMID 21170360, 2010).
Hypercholesterolemia (1 paper, 2022). An increased concentration of cholesterol in the blood. "Interaction analysis showed that ACTB formed the hub of the revealed network, being involved in many interactions with other accessory proteins (e.g., with upregulated CAP1, WDR1, GSN, RHOA, and ARPC1A), suggesting myocardial cytoskeleton rearrangement in response to hypercholesterolemia." (PMID 35806390, 2022).
Hyperkalemia (1 paper, 2022). An abnormally increased potassium concentration in the blood. "In aldosterone-synthase knockout mice, diminished urinary K+ excretion, severe hyperkalemia, and food avoidance were observed, whereas our CAP1/Prss8 knockout mice showed normalized Na+ and K+ balance (data not shown) caused by low but still residual aldosterone concentration." (PMID 35743186, 2022).
Hyperkeratosis (1 paper, 2013). Hyperkeratosis is a histopathological term defining a thickened stratum corneum and may be present in many different skin conditions, with many possible overlaps. "Histological observation of the skin of the CAP1/Prss8lox/Δ;Sox2::CreTg/+ pups right after birth showed hyperkeratosis." (PMID 23405214, 2013). "Nevertheless, those pups were born with an hyperkeratosis as seen in newborns lacking CAP1/Prss8 expression in the epidermis, thus causing death shortly after birth." (PMID 23405214, 2013).
invasive breast carcinoma (1 paper, 2020). A carcinoma that infiltrates the breast parenchyma. "Among 718 women with primary invasive breast cancer within the large population-based prospective Malmö Diet and Cancer Study, tumor-specific CAP1 levels were assessed following thorough antibody validation and immunohistochemical staining of tumor tissue microarrays." (PMID 32560703, 2020).
keratinizing (1 paper, 2022). "In patients with keratinizing squamous cell carcinoma, the CTC subpopulation expressing CAP1 was lower by 26%, compared with that in patients without keratinizing squamous cell carcinoma (P=0.01)." (PMID 37226274, 2022).
keratitis (1 paper, 2022). A corneal disease that is characterized by inflammation of the cornea. "Our results indicated that multiple proteins that were associated with inflammasome and pyroptosis (NLRP3, ASC, CAP1, GSDMD, IL-1β and IL-18) were highly expressed in C. albicans keratitis." (PMID 35463001, 2022).
liver cancer (1 paper, 2020). An epithelial or non-epithelial malignant neoplasm that arises from the liver. "We further referred the biological functions of the DE proteins quantified by i-FASP to the previous reports, and as many as 45.6% of the differential expressed proteins were reported to be associated with liver cancer, such as nestin (NES), and adenylyl cyclase-associated protein 1 (CAP1)." (PMID 32675193, 2020).
lung adenocarcinoma (1 paper, 2022). A carcinoma that arises from the lung and is characterized by the presence of malignant glandular epithelial cells.
monocytic leukemia (1 paper, 2018). "An association of a small proportion of CAP1 with the membrane fraction has been reported in the human monocytic leukemia cell line THP-1 and is likely to represent a common feature of CAP12." (PMID 30018317, 2018).
oligodendroglioma (1 paper, 2018). A well-differentiated (WHO grade II), diffusely infiltrating neuroglial tumor, typically located in the cerebral hemispheres. "Many of these candidates (e.g. ELTD1, SDHB, SEPW1, SLC17A7, SZRD1, THAP3, ZBTB17) are likely to push, whereas others (e.g. CAP1, HBXIP, KLK6, PARK7, PTAFR) might counteract oligodendroglioma development." (PMID 29890994, 2018). "Interestingly, several of these genes (e.g. ELTD1, SDHB, SEPW1, SLC17A7, SZRD1, THAP3, ZBTB17) are likely to push, whereas other genes (e.g. CAP1, HBXIP, KLK6, PARK7, PTAFR) might restrict oligodendroglioma development." (PMID 29890994, 2018).
pneumonia (1 paper, 2018). An acute, acute and chronic, or chronic inflammation focally or diffusely affecting the lung parenchyma, caused by an infection in one or both of the lungs (by bacteria, viruses, fungi, or mycoplasma.). "CAP2 cases and CAP1 controls were matched for age ± 4 years, sex, and Pneumonia Severity Index (PSI) score ± 10 points." (PMID 30263884, 2018).
rhabdomyosarcoma (1 paper, 2020). A rare aggressive malignant mesenchymal neoplasm arising from skeletal muscle. "Rhabdomyosarcoma is also known to have a reduced expression level of hsa-miR-1, which suppresses CAP1 expression." (PMID 31969530, 2020).
schizophrenia (1 paper, 2020). A major psychotic disorder characterized by abnormalities in the perception or expression of reality. "The loss of CAP1 dominance may be caused by weakened top-down regulation by CEN regions, as supported by the observation of failure of reciprocal influence between the right anterior insula and the dorsolateral prefrontal cortex in schizophrenia." (PMID 32116776, 2020).
squamous cell carcinoma (1 paper, 2022). A carcinoma arising from squamous epithelial cells. "It should be noted that in the peripheral blood of patients with squamous cell carcinoma of the oral cavity and larynx, the CTC subpopulation containing CAP1 was most abundantly represented." (PMID 37226274, 2022). "Analysis regarding the type of epithelium revealed that in HNSCC patients with keratinizing squamous cell carcinoma, the CTC subpopulation expressing CAP1 was 26% lower, compared with that in the patients with non-keratinizing squamous cell carcinoma." (PMID 37226274, 2022).
triple-negative breast carcinoma (1 paper, 2018). An invasive breast carcinoma which is negative for expression of estrogen receptor (ER), progesterone receptor (PR), and human epidermal growth factor receptor 2 (HER2). "Furthermore, the highest CAP1 expression was found among triple-negative breast cancer cell lines, and the lowest among hormone receptor positive cell lines (P = 0.01)." (PMID 30524378, 2018).